MLKL (mixed lineage kinase domain like pseudokinase)
Diseases named in the same sentence as MLKL in open-access papers (continued):
Sharing a sentence is not in itself a finding about the gene and the disease.
viral infection (28 papers, 2015 to 2025). "Considering the therapeutic opportunity to inhibit necroptosis pharmacologically, in the light of these results, the analysis of MLKL activation following viral infections utilising this novel detection protocol warrants further investigation." (PMID 38783091, 2024). "The current study provides crucial insights into the expression and correlation of necroptosis markers (MLKL, RIP1 and RIP3) in liver tissue from fatal yellow fever (YF) cases, shedding light on the underlying mechanisms of YF pathology." (PMID 39861792, 2024). "This is further supported by elevated levels of MLKL expression in the hepatic tissue of fatal yellow fever cases as well as by the positive correlation between MLKL and RIP1/3 expression levels." (PMID 39861792, 2024). "Understanding the ubiquitin-mediated regulation of MLKL will be highly relevant in contexts where necroptosis plays a pathophysiological role, such as viral infections, autoinflammatory syndromes and tumour immunity." (PMID 36175538, 2023). "Like a characteristic necroptosis feature of viral infections, phosphorylated MLKL, the major executioner in the necroptosis pathway, was found to be relocalized at the plasma membrane surface of the PSaV-infected LLC-PK cells." (PMID 36735696, 2023). "And through mouse experiments, they confirmed that RIPK/MLKL-mediated necroptosis had a vital function in the destructive inflammation during viral infection." (PMID 35002537, 2021). "To examine the role of MLKL ubiquitylation at K219 in the regulation of necroptosis, viral infection and tissue injury, we generated knock-in mice expressing MlklK219R from the endogenous Mlkl genomic locus." (PMID 34099649, 2021). "MLKL can either protect against viral infection or contribute to viral propagation and/morbidity, depending on the type of virus." (PMID 34071602, 2021). "ZBP1, also known as DAI, was initially identified to induce IFN-mediated MLKL-dependent necroptosis in the context of viral infection." (PMID 34141714, 2021). "Further to questioning the role of MLKL in neurodegeneration, our study also has implications for the relative role of necroptosis in combating bacterial and viral infections in humans." (PMID 32358523, 2020). "It has been shown that RIPK3/MLKL-mediated necroptosis has antiviral function in fibroblast and epithelial cells during lytic virus infection by destroying viral reservoirs." (PMID 32265853, 2020). "Maybe this is an indication of other unknown functions of MLKL in viral infection which are yet to be discovered, or maybe the ability of MLKL to feed back into other modalities of cell death similarly to RIPK3 in the case of influenza infection." (PMID 36175538, 2023). "Collectively, the markedly reduced activation of the key necroptotic kinase RIPK3 and the effector MLKL upon virus infection in Oasl1–/– mice suggests that OASL1 has a pivotal role in the execution of necroptosis in vivo to restrict MCMV replication and elicit antiviral inflammatory responses." (PMID 36604592, 2023). "Our model suggests that the OASL–RIPK3 interaction enhances the formation of the RIPK3 amyloid-like fibril signalling complex, which prolongs RIPK3 activation and drives high levels of MLKL phosphorylation, ultimately inducing robust necroptosis during virus infection." (PMID 36604592, 2023). "Involvement of MLKL in viral infection/response can be divided into two categories: RIPK3 mediated activation of MLKL (Vaccinia virus, Cytomegalovirus, Influenza virus) and MLKL direct targeting (BeAn 58058 poxivirus (BAV), Cotia Poxvirus (COTV) and human HCMV UL36)." (PMID 36175538, 2023). "Furthermore, the effect of RIPK3 and MLKL knockdown on cell death demonstrated their essential roles in virus-induced necroptosis, although the transcription levels of RIPK3 and MLKL were downregulated by virus infection." (PMID 34149651, 2021).
viral infection (continued). "Thus, HSV1 ICP6 RHIM mutant virus infection promotes the rapid assembly of a ZBP1-RIPK3-MLKL necrosome-like complex that drives RIPK3-dependent phosphorylation of MLKL and subsequent death of virus-infected cells." (PMID 30050136, 2018). "This cell death pathway is typically initiated when apoptosis is inhibited, such as during viral infection or caspase-8 dysfunction, and involves receptor-interacting protein kinase 1 (RIPK1), RIPK3, and mixed-lineage kinase domain-like pseudokinase (MLKL)." (PMID 40771812, 2025). "In this study, we investigated the expression and correlation of necroptosis markers MLKL, RIP1 and RIP3 in human liver tissue from fatal cases of yellow fever (YF) using immunohistochemistry (IHC)." (PMID 39861792, 2024). "Although Zbp1 has not yet been studied as an atherosclerosis modifier, it has a role as a sensor of viral infections, in NLRP3 regulation after viral infection, and a role in necroptosis and inflammation via its effects on the RIPK1, RIPK3, and MLKL pathways." (PMID 35052410, 2021). "Given the differential transcriptional upregulation of MLKL and RIPK3, one could hypothesise that these two molecules might also have alternative roles in the response to viral infection or inflammation, independent from each other." (PMID 36175538, 2023). "At the same time, we found that CT26 and CMT93 VT also exhibited natural hyperactivation of GSDMD, GSDME, and p-MLKL, because they were constructed by cas9-expressing lentiviral vector, they could induce natural hyperactivation of GSDMD, GSDME, and p-MLKL through viral infection." (PMID 38740747, 2024). "Moreover, the increased expression of necrosis‐related proteins (p‐MLKL, RIPK1, and RIPK3) induced by viral infection was reduced by pyrogallol, suggesting that pyrogallol could alleviate H1N1 virus‐triggered necrosis." (PMID 38617435, 2024). "The RIPK3-MLKL pathway, which includes receptor-interacting serine/threonine-protein kinase 3 (RIPK3) and mixed lineage kinase domain-like pseudokinase (MLKL), is essential for regulating necroptosis, especially in response to viral infections or cellular stress." (PMID 39735183, 2024). "It will be interesting to determine if other viruses including Sars-CoV-2 and its variants can also encode for such MLKL-like decoy-substrates and perhaps investigate if MLKL is required for other homeostatic responses following viral infection rather than merely cell death." (PMID 36175538, 2023). "For viral infection-induced necroptosis, RIPK3 and MLKL, but not RIPK1, are required and another protein, Z-DNA-binding protein 1 (ZBP1), also known as DNA-dependent activator of IFN regulatory factors (DAI), functions upstream of RIPK3-MLKL to initiate the formation of the necrosome." (PMID 36703228, 2023).
ovarian carcinoma (24 papers, 2014 to 2024). A malignant neoplasm originating from the surface ovarian epithelium. "Low expression of MLKL is associated with poor prognosis in cervical squamous cell cancer, ovarian cancer, gastric cancer, and pancreatic adenocarcinoma." (PMID 38474369, 2024). "Ling He and his group have figured out that low expression of MLKL was significantly associated with a shortened disease-free survival and overall survival in primary ovarian cancer patients." (PMID 37169000, 2023). "Mechanistically, dying ovarian cancer cells exhibit oligomerization and relocalization to plasma membrane of MLKL, which is a hallmark of necroptosis." (PMID 32151027, 2020). "In ovarian cancers, MLKL increases the susceptibility of cells to necroptosis induced by CNLs." (PMID 38474369, 2024). "Additionally, low expression of MLKL is strongly associated with poor prognosis in ovarian cancer patients." (PMID 33348858, 2020). "Low expression level of MLKL was significantly correlated with shorter overall survival of gastric cancer, ovarian cancer, and cervical squamous cell cancer." (PMID 36238158, 2022). "MLKL is also downregulated in pancreatic cancer and cervical squamous cell carcinoma, where low levels of MLKL in plasma predict poor prognosis in pancreatic and ovarian cancer." (PMID 36238158, 2022). "Taken together, these findings suggest that ceramide nanoliposomes elicit a cytotoxic effect by inducing MLKL-dependent necroptosis in ovarian cancers." (PMID 32151027, 2020). "Recent studies of ceramide-based cancer therapies revealed that treatment of ovarian cancer cells with ceramide nanoliposomes evoked MLKL-driven necroptosis independently of RIPK1/3." (PMID 32151027, 2020). "This is supported by the observations that the inhibition of RIPK1 and MLKL protect from vaccinia-mediated necroptosis in ovarian cancer cell." (PMID 30665407, 2019). "We first investigated the expression of RIPK1, RIPK3, caspase-8 and MLKL in a panel of ovarian cancer cell lines as well as HeLa cells." (PMID 29238045, 2017). "Importantly, the anti-tumor activities of CNLs correlated with MLKL expression in ovarian cancer cell lines, implying the involvement of MLKL expression in the therapeutic effectiveness of CNLs." (PMID 38474369, 2024). "In addition, MLKL expression is significantly decreased in pancreatic adenocarcinomas and ovarian cancer tissues compared to the adjacent normal tissues, and this reduction was proven to be associated with disease progression." (PMID 36361505, 2022). "A small number of studies have suggested that MLKL expression may act as a prognostic biomarker in pancreatic and ovarian cancer." (PMID 35912268, 2022). "MLKL is also downregulated in pancreatic and cervical squamous cell carcinomas, where low levels of MLKL in plasma predict poor prognosis in pancreatic and ovarian cancers." (PMID 36170029, 2022). "The inhibition of RIPK1 and its substrate MLKL attenuate ovarian cancer cell death." (PMID 30665407, 2019). "In ovarian cancer cells, inhibition of BMI1 gene can induce activation of RIPK1-RIPK3 complex, which phosphorylates its downstream substrate MLKL and enhances necrosis." (PMID 33927214, 2021). "This was demonstrated by a greater expression and activation of caspase 3 and 8, RIPK3 (Receptor Interacting Serine/Threonine Kinase 3) and MLKL (Mixed Lineage Kinase Domain Like Pseudokinase), in OVCAR3 and three primary ovarian cancer cell lines derived from patients." (PMID 35669542, 2022). "Besides its widely documented apoptotic anticancer activity, berberine promoted necroptosis in ovarian cancer cells and in three patient-derived primary ovarian cancer cell lines (POCCLs) by activating RIP3 and MLKL." (PMID 33467668, 2021).
ovarian carcinoma (continued). "CNLs activate MLKL-governed necroptosis independent of RIPK3 in ovarian cancer cells." (PMID 38474369, 2024).
atherosclerosis (22 papers, 2020 to 2026). A disease characterized by the build-up of fatty material and calcium deposition in the arterial wall resulting in partial or complete occlusion of the arterial lumen. "MLKL loss also distinctly caused a select reduction in circulating cholesterol, akin to a recent report in a model of atherosclerosis." (PMID 39532538, 2025). "MLKL-mediated necroptosis has long been linked to various age-related pathologies including neurodegeneration, atherosclerosis and male reproductive decline, however many of these attributions remain controversial." (PMID 39572538, 2024). "Overexpression of MLKL inhibited autophagy flux and activated inflammation in atherosclerosis, which was associated with a mechanistic target of rapamycin (mTOR)-dependent signaling pathway." (PMID 36765043, 2023). "Beyond infections, aberrant MLKL activation contributes to a wide range of chronic diseases, including atherosclerosis, cardiometabolic disorders, liver disease, neurodegeneration, and cancer." (PMID 41897296, 2026). "In another study, oxidized low-density lipoprotein (OX-LDL) worsens atherosclerosis by inhibiting autophagy through MLKL." (PMID 40070567, 2025). "Pharmacological inhibition of MLKL with calycosin significantly improves atherosclerosis, reducing necrotic core area and vascular inflammation, as well as foam cell formation." (PMID 40070567, 2025). "Meanwhile, the RIPK1/RIPK3/MLKL pathway-mediated necroptosis plays a significant role in various CVDs, including atherosclerosis, ischemia-reperfusion injury, myocardial infarction, and myocarditis." (PMID 39301029, 2024). "RIPK3 and MLKL have been demonstrated to mediate macrophage necroptosis during atherosclerosis development." (PMID 37863894, 2023). "At baseline (0 weeks WD), very low levels of RIPK1, RIPK3, and MLKL were observed in the atherosclerosis-prone aortic arch of both ApoE−/− and ApoE−/− Fbn1C1039G+/− mice but the expression levels increased during plaque progression." (PMID 35625752, 2022). "Necroptosis also has a prominent effect in cardiomyocytes loss during acute viral myocarditis, I/R injury, and atherosclerosis through its ligand death receptors including receptor-interacting protein 1, 3 (RIP1, 3) and mixed lineage kinase domain-like (MLKL)." (PMID 35205167, 2022). "In atherosclerosis, lncRNA-FA2H-2 transcriptionally inhibited MLKL expression and loss of lncRNA-FA2H-2 led to the activation of inflammation and inhibition of autophagic flux which is dependent on mTOR pathway." (PMID 34759263, 2021). "As RIPK3 is necessary for necroptosis – and as necroptosis is considered to be inherently inflammatory – researchers have suggested that RIPK3 or MLKL should be targeted to decrease atherosclerosis severity in the clinical setting." (PMID 31953345, 2020). "Additionally, two studies highlight the critical role of MLKL signaling pathway in regulating autophagy during atherosclerosis onset." (PMID 40070567, 2025). "For example, through binding mixed lineage kinase domain-like protein (MLKL)promoter, lncRNA FA2H-2 regulates autophagy and inflammation in atherosclerosis.After the suppression of MLKL expression in SMCs and ECs in response to ox-LDL,autophagic flux is enhanced and inflammation is diminished." (PMID 39077721, 2022). "Further investigation into the role of MLKL in atherosclerosis is merited." (PMID 33142926, 2020). "The role of MLKL in atherosclerosis is, however, seemingly complex." (PMID 33142926, 2020). "Recently, Kamal and coworkers have found that MLKL is associated to hallmarks of atherosclerosis with and without type II diabetes mellitus, which could be a potential drug target for treating atherosclerotic patients." (PMID 37924005, 2023). "Generally, MLKL-dependent and MLKL-independent necrosis can be seen in multiple tissues or organs, which may be related to the pathophysiology of multiple diseases, such as heart disease, atherosclerosis, brain disease, infection, and inflammation." (PMID 33064829, 2021).
atherosclerosis (continued). "Cumulatively, the data suggest that RIPK1 is emerging as a master switch that controls inflammation and cell survival in atherosclerosis progression, and phosphorylation of RIPK1, RIPK3 and MLKL are definitive indicators of necroptosis activation." (PMID 37863894, 2023). "Compared with normal arteries, the expression of RIP3 and MLKL mRNA was significantly increased in advanced atherosclerotic plaques, and RIP3−/− mice are protected from the development of atherosclerosis." (PMID 35464769, 2022). "In atherosclerosis, elevated levels of RIPK1, RIPK3, and phosphorylated MLKL have been detected in unstable atherosclerotic plaques from humans and Ripk3-deficient mice develop significantly smaller advanced aortic atherosclerotic lesions." (PMID 34572045, 2021). "In the context of atherosclerosis, lncRNA FA2H-2 regulates autophagy and inflammation via binding the promoter of mixed lineage kinase domain-like protein (MLKL) gene." (PMID 32772181, 2020). "In patients with atherosclerosis, the expression levels of RIPK3 protein and MLKL are elevated." (PMID 39301029, 2024).
colorectal cancer (21 papers, 2018 to 2026). A primary or metastatic malignant neoplasm that affects the colon or rectum. "For instance, a variety of cancers displayed low/loss expression of RIP3/MLKL and necroptotic resistance, while others including pancreatic cancer, colorectal cancer and head and neck caner showed high necroptotic rates." (PMID 38926796, 2024). "The RIPK1 inhibitor Necrostain-1 inhibits colorectal cancer cell necroptosis via the RIPK1/RIPK3/MLKL signaling pathway." (PMID 36604411, 2023). "The recent study found that TRAF6 inhibits necroptosis in colorectal cancer cells via the RIPK1/RIPK3/MLKL signaling pathway." (PMID 36604411, 2023). "Activated MLKL inhibited autophagy flux in mouse dermal fibroblasts and HT-29 human colorectal cancer cells." (PMID 36765043, 2023). "Other chemotherapeutic agents such as 5-Fluorouracil (5-FU), etoposide, and camptothecin were shown to induce RIP1/MLKL-dependent, but RIP3-independent necroptosis in caspase-3-deficient colorectal cancer cells." (PMID 30583560, 2018). "The recent study demonstrated that TRAF6 promotes colorectal cell progression by inhibiting the RIPK1/RIPK3/MLKL necroptosis signaling pathway, which may provide a new therapeutic target for colorectal cancer." (PMID 36604411, 2023). "These clinical findings indicate that low MLKL expression level may be prognostic for the malignant progression of colorectal cancer." (PMID 33767595, 2021). "While treatment with TNF/SMAC mimetic (SM)/z-VAD-FMK (TSZ) caused time- and RIPK1-dependent necroptosis in human colorectal cancer HT-29 cells, mouse dermal fibroblasts (MDFs) and murine L929 cells, TSZ also triggered ubiquitylation of endogenous MLKL in all these cell types." (PMID 34099649, 2021). "Moreover, the IL-6-induced increase in pSTAT3 in the context of knocked down MLKL expression was also found in colorectal carcinoma HT-29 cells." (PMID 33767595, 2021). "Our data therefore suggest that the blockage MLKL/JNK/IL-8 during conventional radiotherapy might enhance the efficacy of radiotherapy in colorectal cancer." (PMID 31706322, 2019). "MLKL may serve as a promising target to block tumor regeneration and participate in the regulation of necroptosis pathway, thereby improving the efficacy of radiation therapy for colorectal cancer." (PMID 36353119, 2022). "Like apoptosis and necrosis this novel cell death manner could also induce tumor cells nearby growth by upregulating the phosphorylation of RIP1 and RIP3, leading to the formation of the RIP1/RIP3 necrosome complex and subsequent phosphorylation of MLKL in some colorectal cancer cells." (PMID 31706322, 2019). "This novel pathway provided new insight into understanding the mechanism of tumor radioresistance and repopulation, and MLKL/JNK/IL-8 could be developed as promising targets for blocking tumor repopulation to enhance the efficacy of colorectal cancer radiotherapy." (PMID 31706322, 2019). "Transient and stable overexpression of TRAF6 in colorectal cancer cells significantly decreased the protein levels of RIPK1 and p-RIPK1 as well as downstream p-RIPK3 and p-MLKL produce inhibition." (PMID 36604411, 2023). "Knockdown of TRAF6 in colorectal cancer cells significantly up-regulated the protein levels of RIPK1 and p-RIPK1 and downstream p-RIPK3 and p-MLKL." (PMID 36604411, 2023). "Comparison of their expression in HUVEC and HT-29, a human colorectal carcinoma cell line, revealed that RIPK1 and MLKL were expressed in HUVEC and HT29, while RIPK3 was normally expressed in HT29 but at an extremely low level in HUVEC." (PMID 32332696, 2020).